IGF1R (insulin like growth factor 1 receptor)
Diseases named in the same sentence as IGF1R in open-access papers (continued):
Sharing a sentence is not in itself a finding about the gene and the disease.
pulmonary fibrosis (13 papers, 2013 to 2025). Chronic progressive interstitial lung disorder characterized by the replacement of the lung tissue by connective tissue, leading to progressive dyspnea, respiratory failure, or right heart failure. "Despite these evidences, a recent study investigated the role of IGF-1R in experimental pulmonary fibrosis by exposing IGF-1R deficiency mice to bleomycin." (PMID 30018981, 2018). "Our earlier findings demonstrated that miR-15a-5p regulates pulmonary fibrosis by targeting IGF1R-mediated autophagy, while IGF1R itself undergoes CF, a post-translational modification that exacerbates fibrotic progression." (PMID 40746334, 2025). "In experimental pulmonary fibrosis and scleroderma-related skin fibrosis models, IGF-1R inhibition reduces fibroblast proliferation and collagen deposition." (PMID 40718626, 2025). "To investigate the functional impact of CF on IGF1R in pulmonary fibrosis, we employed a BLM-induced murine model using conditional FUT8 knockout (CKO) mice." (PMID 40746334, 2025). "Our data are therefore in line with previous reports showing that blocking IGF1R signaling ameliorates bleomycin-induced pulmonary fibrosis in experimental mice." (PMID 35741102, 2022). "Blockade of IGF-1R activation in bleomycin-induced mouse lung fibrosis also displayed activities in induction of fibroblast apoptosis and resolution of pulmonary fibrosis." (PMID 24400868, 2014). "This aligns with IGF1R’s facilitation of pulmonary fibrosis through the TGF-β/Smad/STAT cascade." (PMID 38059910, 2023). "Mechanistically, miR-15a-5p deficiency promotes core fucosylation -dependent stabilization of the membrane protein IGF1R, which activates the PI3K/AKT pathway to suppress alveolar epithelial cell autophagy, thereby exacerbating pulmonary fibrosis." (PMID 40746334, 2025). "Under pathological conditions such as idiopathic pulmonary fibrosis (IPF), alveolar epithelial cells release IGF-1, which activates IGF-1R on adjacent normal alveolar epithelial cell surfaces, and further activates downstream PI3K and AKT kinases." (PMID 39638246, 2024). "Lung tissues derived from bleomycin-treated mice and explanted IPF lungs revealed upregulation of IGF1 in parallel to downregulation of IGF1R, in addition to upregulation of several IGF binding proteins (IGFBPs) in lung fibrosis." (PMID 35741102, 2022). "Other studies also demonstrated that senescent AEC2s, through insulin-like growth factor-1 receptor or PAI-1 signalling, are necessary for the progression of pulmonary fibrosis and serve as chronic stimuli for macrophage activation in lung fibrosis." (PMID 34209809, 2021). "Blockade of the IGF-1/IGF-1R pathway by an IGF-1R antibody induces fibroblast apoptosis and subsequent resolution of pulmonary fibrosis." (PMID 30018981, 2018). "While expression of genes coding for soluble mediators (e.g. cytokines) were unchanged, receptors for several mediators known to participate in lung fibrosis were up-regulated (CCR2, FGFR2, FLT1, IGF1R, IL1R1 and IL6R)." (PMID 23844029, 2013). "Interestingly, IGF1R functions through the transforming growth factor (TGF)-β/Smad/STAT cascade, as demonstrated in idiopathic pulmonary fibrosis." (PMID 38059910, 2023). "Last but not least, intervention with monoclonal antibodies against IGF1R attenuates bleomycin-induced pulmonary fibrosis." (PMID 35741102, 2022). "Furthermore, activation of the IGF-1/IGF-1R axis led to the generation of reactive oxygen species (ROS), which promotes epithelial-mesenchymal transition (EMT) in alveolar epithelial cells, thereby accelerating pulmonary fibrosis." (PMID 39638246, 2024).
acute myeloid leukemia (12 papers, 2011 to 2024). Acute myeloid leukemia (AML) is a group of neoplasms arising from precursor cells committed to the myeloid cell-line differentiation. "Both, miR-223 and miR-223* target the insulin-like growth factor 1 receptor, and high miR-223* levels were associated with increased overall survival in patients with acute myeloid leukemia." (PMID 27166999, 2016). "BMS-536924 is a dual IGF1R/IR kinase inhibitor that has been experimentally proven to inhibit acute myeloid leukemia (AML) proliferation and serve as a potential therapeutic target for AML." (PMID 37976136, 2023). "Previous studies demonstrated that Sox4, RasGRP1, RasGRP3, IGF1R, CDK6, and LEF1 are the key oncogenes/tumor suppressor genes in acute myeloid leukemia." (PMID 31242922, 2019). "In acute myeloid leukemia (AML) cells, IGF1R is one of the most abundantly phosphorylated receptor tyrosine kinases, promoting cell growth through the PI3K/Akt signaling pathway." (PMID 25092925, 2014). "Another lncRNA involved in acute myeloid leukemia (AML) is IRAIN, which is produced from the insulin-like growth factor type I receptor (IGF1R) imprinted locus." (PMID 25927065, 2015).
brain tumor (12 papers, 2010 to 2025). "Of note is the fact that both insulin receptor and IGF-1R were repeatedly shown to be associated with brain tumour development, proliferation and response to therapy in humans." (PMID 20436918, 2010). "Future studies should explore the potential of IGF-1R-targeted ligands as delivery vehicles for therapeutic agents against brain tumors, given their demonstrated ability to efficiently and rapidly transport biologics across the BBB." (PMID 40806198, 2025). "Here, we targeted the IGF pathway using ceritinib, an off-target inhibitor of the IGF1 receptor (IGF1R) and insulin receptor (INSR), in a pediatric patient with an unclassified brain tumor and a notch receptor 1 (NOTCH1) germline mutation." (PMID 31480400, 2019). "We previously showed that ceritinib can inhibit the IGF receptor IGF1R in a particular subtype of pediatric brain tumors at a concentration that is achievable in vivo." (PMID 31480400, 2019). "We identified several annotated brain tumor data sets in which we could compare IGF-1R expression in specimens of different tumor grades or from patients with differential survival outcomes." (PMID 30231881, 2018). "Previous studies suggest that the differential expression of IGF1R may be important in autocrine stimulation of brain tumor cell growth." (PMID 23840654, 2013).
endometriosis (12 papers, 2015 to 2025). The growth of functional endometrial tissue in anatomic sites outside the uterine body. "To further explore the role of Igf-1 in mice with endometriosis-associated pain, we inhibited Igf-1r using linsitinib, a selective IGF-1R inhibitor that prevents autophosphorylation and activation of downstream signaling." (PMID 31291762, 2019). "In the first reported example of sponging in endometriosis, decreased levels of the H19 lncRNA was shown to be associated with an increase in let-7 miRNA activity, which inhibits IGF1R expression resulting in the reduced proliferation of endometrial stroma cells." (PMID 34768856, 2021). "The epithelium of the endometriosis lesion expresses high levels of IGF-1R and c-MET, the receptor for IGF1/2 and HGF, respectively." (PMID 35740424, 2022). "H19 has been shown to regulate several pathways that are important in endometriosis, IGF1R, ITGB3, IER3, and ACTA2." (PMID 36232884, 2022). "H19 has been shown regulate several pathways that are relevant in endometriosis including IGF1R, ITGB3, IER3, and ACTA2." (PMID 34768856, 2021). "In endometriosis, the upregulation of H19 expression was shown to promote endometriotic stromal cell proliferation through the downregulation of let-7 to target IGF1R." (PMID 29116025, 2017). "In this report, we show that the expression of both H19 and Igf1r is significantly decreased in the eutopic endometrium of women with endometriosis." (PMID 26089099, 2015). "On the other hand, IGF-1R inhibitors may alleviate pain in mice with injury of the sciatic nerve, bone cancer pain, and endometriosis-induced hyperalgesia." (PMID 37242543, 2023). "Disruption of the H19/Let-7/IGF1R regulatory pathway may contribute to impaired endometrial preparation and receptivity in women with endometriosis." (PMID 36232884, 2022). "By being exposed to the same FF after ovulation, the endometriosis cells that express IGF-1R may also respond with a growth signal with the clonal expansion of stem/progenitor cells." (PMID 35740424, 2022). "Perturbation of this newly identified H19/Let-7/IGF1R regulatory pathway may contribute to impaired endometrial preparation and receptivity in women with endometriosis." (PMID 26089099, 2015). "We propose that perturbation of this newly identified H19/Let-7/IGF1R regulatory pathway may contribute to impaired endometrial preparation and receptivity for pregnancy in women with endometriosis." (PMID 26089099, 2015). "Given the concomitant downregulation of H19 and Igf1r in the eutopic endometrium of endometriosis (Fig1A and B), we sought to determine whether H19, through sequestering let-7, might regulate Igf1r expression in the human endometrial stromal cells." (PMID 26089099, 2015). "Normal eutopic endometrium grows quickly during the proliferative phase of the menstrual cycle, but our findings suggest that alterations of the H19/Let-7/IGF1R pathway may impair eutopic endometrial cell growth in women with endometriosis." (PMID 26089099, 2015). "Alterations in this H19/Let-7/IGF1R-mediated regulation of endometrial cell proliferation may represent a potential mechanism for infertility in women with endometriosis." (PMID 26089099, 2015). "Together, these results suggested that decreased expression of H19 and Igf1r might contribute to impaired development and function of eutopic endometrium in patients with endometriosis." (PMID 26089099, 2015). "However, there are studies that suggest IGF-1R antagonism may alleviate pain-related behaviors in mice with injury of the sciatic nerve, pain behaviors from bone cancer, and hyperalgesia from endometriosis." (PMID 37242543, 2023). "In addition, it has been reported that H19 can function as a molecular sponge of let-7 and H19/Let-7/IGF1R regulatory pathway may related with impaired endometrial preparation and receptivity for pregnancy in women with endometriosis." (PMID 27580177, 2016).
endometriosis (continued). "However, it is not known whether the expressions of Igf1r and/or Igf1 are altered in the eutopic endometrium of women with endometriosis and if so, what the underlying mechanism might be." (PMID 26089099, 2015). "The results of some studies have shown reduced H19 expression in endometriosis patients to be correlated with reduced levels of IGF1R mRNA in the eutopic endometrium compared to women without endometriosis." (PMID 38791310, 2024). "Due to the fact that women with unexplained infertility show reduced expression of H19 in the eutopic endometrium, H19 regulates let-7 and let-7 targets IGF1R, and it is useful to determine the role of H19 in the endometrium and its relationship to IGF signaling in endometriosis." (PMID 38791310, 2024). "Given that women with unexplained infertility show decreased H19 expression in their eutopic endometrium and that H19 regulates let-7 which targets Igf1r, we wished to determine the physiological role of H19 in the endometrium and its relationship with the IGF signaling in endometriosis." (PMID 26089099, 2015). "Our results show that women with endometriosis have decreased H19 expression as well as a concomitant decrease in the level of Igf1r mRNA in the eutopic endometrium compared to women without endometriosis." (PMID 26089099, 2015).
Glucose intolerance (12 papers, 2011 to 2025). Glucose intolerance (GI) can be defined as dysglycemia that comprises both prediabetes and diabetes. "In murine studies, deletion of the IGF-1R in skeletal muscle resulted in glucose intolerance issues ultimately leading to T2D at an early age, because, although they express insulin receptors, they cannot form hybrid or IGF-1 receptors." (PMID 26733412, 2016). "One previous study found that the absence of IGF1R in beta cells in mice caused glucose intolerance and deficiency in insulin secretion." (PMID 38274107, 2023). "In addition, old male Igf1r+/− mice develop glucose intolerance (with females exhibiting a tendency to glucose intolerance)." (PMID 22132081, 2011). "We previously reported that the systemic inhibition of insulin receptor (IR) and IGF-1 receptor (IGF1R) by the administration of OSI-906 (linsitinib), a dual IR/IGF1R inhibitor, induced glucose intolerance, hepatic steatosis, and lipoatrophy in mice." (PMID 33105604, 2020).
intrauterine growth restriction (12 papers, 2009 to 2026). "Rare human homozygous, heterozygous or compound heterozygous mutations in IGF1R cause intrauterine growth restriction, reduced postnatal growth, short stature and microcephaly." (PMID 39809772, 2025). "Loss-of-function mutations in IGF1R have been reported in children presenting with intrauterine growth restriction, short stature, and elevated IGF-1 levels." (PMID 36530175, 2022). "In a 30 WG fetus with intrauterine growth restriction and hypotelorism leading to unknown fetal prognosis, ES evidenced a causative heterozygous IGF1R truncating variant inherited from the mother, who was of short stature." (PMID 37035737, 2023). "Mutations in the insulin-like growth factor 1 receptor (IGF1R) gene are associated with impaired growth, intrauterine growth restriction (IUGR), low birth weight and/or length, and postnatal SS." (PMID 42073036, 2026). "We report the case of a girl born at term after severe symmetric fetal growth restriction (FGR), identified prenatally through trio whole-exome sequencing as carrying compound heterozygous IGF1R variants-c.155G>C (p.Cys52Ser) and c.3476A>G (p.Asp1159Gly)." (PMID 42022487, 2026). "Intrauterine growth restriction (IUGR) leads to insulin-like growth factor 1 receptor (IGF-1R)-mediated fetal growth retardation through impaired oxygen and nutrient delivery." (PMID 34680478, 2021).
lymph node metastasis (12 papers, 2010 to 2022). "CBLB could repress IGF-1R and decrease the risk of developing lymph node metastasis in patients with GC." (PMID 30111747, 2018). "Furthermore, among patients without EGFR mutation, those who have at least one polymorphic A allele of IGF1R rs7166348 have an increased incidence of lymph node metastasis when compared with those patients homozygous for GG (OR, 2.75; 95% CI, 1.20–2.31)." (PMID 27213344, 2016). "Univariate logistic regression analysis showed strong association between IGF1-R expression and ERRB4 alterations in the primary tumor or lymph node metastasis (odds ratio: 54.0; p < 0.01)." (PMID 36077746, 2022). "On univariate analysis, three factors, IGF1R overexpression, IGF1R-positive and IGFBP3-negative expression, and lymph node metastasis, were significantly associated with worse overall survival." (PMID 23962053, 2013). "The expression of circ‐IGF1R in the present study correlated with tumor and lymph node metastasis." (PMID 32107851, 2020). "Indeed, IGF-1R expression is an independent predictor of survival in patients and has been correlated with a worse prognosis and lymph node metastasis." (PMID 30111747, 2018). "Immunohistochemical analyses revealed that IGF1R expression was associated with histological grade and lymph node metastasis, but not with surgical stage." (PMID 24904527, 2014). "Because IGF1R status is deeply associated with IGF1R and IGFBP3 status, multivariate analysis was performed with two factors: IGF1R-positive and IGFBP3-negative expression, and lymph node metastasis." (PMID 23962053, 2013). "IGF1R-positive and IGFBP3-negative expression and lymph node metastasis were independent predictors of poor prognosis." (PMID 23962053, 2013). "The multivariate survival analysis indicated that IGF1R-positive and IGFBP3-negative expression, along with lymph node metastasis, were independent prognostic indicators." (PMID 23962053, 2013). "Abnormal IGF1R and VEGF-C expressions, therefore, might constitute important markers for lymph node metastasis of endometrial adenocarcinoma and might be potentially useful for evaluating disease prognosis." (PMID 24904527, 2014). "The positivity rate of IGF-1R in the lymph node metastasis group (91.67%) was not significantly higher than that in the lymph node metastasis-free group (93.33%) (P > 0.05)." (PMID 22072919, 2011).
myocardial infarction (12 papers, 2009 to 2024). Gross necrosis of the myocardium, as a result of interruption of the blood supply to the area, as in coronary thrombosis. "Insulin-like growth factor 1 receptors (IGF-1R)/nitric oxide (NO) signaling pathway can promote serum angiogenesis in patients with myocardial infarction." (PMID 39350967, 2024). "The expression of IGF-1R has been shown to be increased in the left ventricle of rats with hypertrophic cardiomyopathy secondary to norepinephrine infusion and also in acute myocardial infarction." (PMID 19818143, 2009). "Thus, NAR improved the angiogenesis of HUVECs by regulating the miR-223-3p/IGF1R axis, suggesting that it has the potential to promote angiogenesis in mice with myocardial infarction." (PMID 38406772, 2023). "However, the expression of its receptor IGF-1R was increased in post myocardial infarction hypertrophic cardiomyopathy only." (PMID 19818143, 2009). "Echocardiographic recordings and myocardial sampling for measurements of gene expressions of IGF-1, its receptor (IGF-1R), TGFβ and of cyclins A, B, D1, D2, D3 and E, were obtained in 8 dogs with a healed myocardial infarction, 8 dogs after 7 weeks of overpacing and in 7 healthy control dogs." (PMID 19818143, 2009). "After co-culturing serum exosomes from patients with myocardial infarction with human umbilical vein endothelial cells, cell proliferation, migration, and angiogenesis were observed, which occurred due to the reduction in miR-143 expression, the targeting of IGF-1R, and enhanced NO production." (PMID 39350967, 2024). "On the other hand, it has been also been reported that CVDs such as myocardial infarction (MI) stimulate EAT formation via the insulin-like growth factor 1 receptor (IGF1R)-dependent signaling pathway, suggesting a correlation between CVD progression and EAT." (PMID 37106699, 2023). "Importantly, IGF-1R inhibition was sufficient to promote resistance against renal IR injury which could be of interest in the context of solid organ transplantation, vascular surgery, or myocardial infarction." (PMID 39759002, 2024). "On the other hand, it was also reported that the deletion of miR-150 in mice protected against myocardial-infarction-induced AKI through an anti-apoptosis and anti-fibrosis mechanism by targeting insulin-like growth factor-1 receptor (IGF-1R)." (PMID 37761260, 2023). "On the other hand, IGF1R, through the IGF1-IGF1R system, modulates the proliferation of myocytes after myocardial infarction." (PMID 35625854, 2022). "Regardless of age, numerous studies showed that promoting IGF1R-dependent anti-apoptotic signaling is cardioprotective in pathological conditions, such as doxorubicin-induced cardiotoxicity or myocardial infarction." (PMID 36078109, 2022).